ENSG00000285245 (novel protein)
Gene: Protein-coding gene on chromosome 9 (133,098,121 to 133,163,914, reverse strand). Ensembl gene ENSG00000285245.
Genetic constraint (gnomAD): Loss-of-function variants: 52 observed, 108.28 expected, observed/expected ratio (o/e) 0.48, 90% interval 0.38 to 0.61. Missense variants: 1,044 observed, 1,263.1 expected, observed/expected ratio (o/e) 0.83, 90% interval 0.79 to 0.87. Synonymous variants: 525 observed, 515.64 expected, observed/expected ratio (o/e) 1.02, 90% interval 0.95 to 1.09.